BMF (Bcl2 modifying factor)
Description:
May play a role in apoptosis. Isoform 1 seems to be the main initiator.
Synonyms: FLJ00065
Tractability: Small molecule: a structure with a bound ligand is known. Antibody: its Gene Ontology location is reachable by antibodies, with high confidence.
Gene: Protein-coding gene on chromosome 15 (40,087,889 to 40,108,928, reverse strand). Ensembl gene ENSG00000104081.
Subcellular location (Human Protein Atlas): Cytosol
Pathways (Reactome):
Programmed Cell Death: Activation of BMF and translocation to mitochondria; BH3-only proteins associate with and inactivate anti-apoptotic BCL-2 members
Gene Ontology:
Molecular function: protein binding
Biological process: anoikis; negative regulation of autophagy; positive regulation of apoptotic process; positive regulation of protein-containing complex assembly; positive regulation of release of cytochrome c from mitochondria; apoptotic process
Cellular component: cytosol; mitochondrial outer membrane; myosin complex; plasma membrane
Genetic constraint (gnomAD): Loss-of-function variants: 10 observed, 21.53 expected, observed/expected ratio (o/e) 0.46, 90% interval 0.29 to 0.79. The upper end of that interval is the gene's LOEUF score, 0.79, which puts it in group 3 of 6, group 1 being the genes least tolerant of losing a copy. Missense variants: 206 observed, 235.37 expected, observed/expected ratio (o/e) 0.88, 90% interval 0.78 to 0.98. Synonymous variants: 87 observed, 92.86 expected, observed/expected ratio (o/e) 0.94, 90% interval 0.79 to 1.12.
Homologues: Orthologues: chimpanzee BMF (99% identical), macaque BMF (96% identical), dog BMF (93% identical), guinea pig BMF (91% identical), rabbit BMF (91% identical), pig BMF (91% identical), mouse Bmf (88% identical), rat Bmf (59% identical), tropical clawed frog bmf (45% identical), zebrafish bmf2 (24% identical).
Diseases named in the same sentence as BMF in open-access papers:
BMF is named in the same sentence as 41 diseases in open-access papers, as found by Europe PMC text mining. Sharing a sentence is not in itself a finding about the gene and the disease. The quoted sentences say what the papers report.
colon cancer (9 papers, 2014 to 2023). "The tolerance of colon cancer cell lines to oxaliplatin involves the down-regulation of Bcl2-modifying factor (BMF), ATG7, and Beclin-1." (PMID 31658599, 2019). "Studies have reported that HDAC8 inhibits apoptosis in colon cancer cells by repressing Bcl-2-modifying factor (BMF) transcription." (PMID 30687400, 2018). "Treatment of colon cancer cells with a p300 inhibitor attenuated significantly the basal expression levels as well as the dose-dependent induction of BMF by MSP." (PMID 25321483, 2014). "Induction of pro-apoptotic APAF1, BAK, BIM, and BMF, and loss of anti-apoptotic BCLXL occurred within 12 h of MSP treatment, in both HCT116 and HT29 colon cancer cell lines." (PMID 25321483, 2014). "Besides its role in BRCA, BMF is also an important prognostic marker for patients with other cancers, such as colon cancer and hepatocellular carcinoma." (PMID 35707265, 2022). "Methylselenopyruvate is an α-keto acid metabolite of methylselenocysteine which acts as a histone deacetylase 8 (HDAC8) inhibitor that can restore Bcl2 modifying factor (BMF) downregulation and thereby activates apoptosis in colon cancer cells." (PMID 34950627, 2021). "The BCL-2 modifying factor, BMF which is a pro-apoptotic activator, was reported to be conjointly downregulated by HDAC1 and 8; inhibition of HDAC8 by methylselenopyruvate in colon cancer cells restored BMF downregulation and thereby activated apoptosis." (PMID 31096697, 2019). "We then treated cells with BAD, NOXA, PUMA, BMF, and HRK BH3 peptides, which have variable affinities for anti-apoptotic proteins, and compared the mitochondrial depolarization between parental and 5-FU-resistant colon cancer cells." (PMID 31638265, 2019).
breast carcinoma (8 papers, 2015 to 2025). "According to our previous results of mRNA sequencing 24, we found that mRNA level of BMF was significantly upregulated in breast cancer cells." (PMID 35280673, 2022). "Similar to HOXD-AS1, the STARD13 (DLC2, a RhoGAP) 3’UTR acts as a ceRNA and increases Bcl-2 modifying factor (BMF) expression by competitively binding with miR-125b in breast cancer." (PMID 34663417, 2021). "In qRT-PCR result, the expression of BMF in MCF-7 breast cancer cells was also lower than the other breast cancer cell lines." (PMID 26103053, 2015). "Another research showed that STARD13 3′UTR could play as a ceRNA for BMF to enhance apoptosis and be used as a potential therapeutic target in breast cancer cells." (PMID 37794108, 2023). "Moreover, a remarkable decrease of BMF expression was reported in breast cancer tissues compared to that of paracancerous tissues." (PMID 35280673, 2022). "In our study, we elucidated that RBMS2, together with BMF, could enhance apoptosis of breast cancer cells to promote the sensitivity to DOX." (PMID 35280673, 2022). "Therefore, we hypothesized that RBMS2 could sensitize breast cancer cells to DOX via inducing apoptosis regulated by BMF expression." (PMID 35280673, 2022). "In summary, BMF could rescue the apoptosis of breast cancer cells induced by RBMS2." (PMID 35280673, 2022). "The results demonstrated that the expression levels of OLR1, ADIPOR1, CEACAM6, DNASE2, CD53, BMF, and CAMP were significantly elevated in breast cancer samples compared to healthy controls (p < 0.05)." (PMID 40282270, 2025). "Other co-expressed genes such as BMF, CD53, PIK3R1, and CWF19L2 have also been reported in breast cancer studies." (PMID 40282270, 2025). "Then, we discovered that BMF expression was downregulated and positively correlated with RBMS2 expression in breast cancer and normal tissues from our hospital and TCGA databases." (PMID 35280673, 2022). "Similar results were found using an alternative cellular model, the MCF-7 breast cancer epithelial cell line, in which FOXM1 repression also induces BMF upregulation." (PMID 34035233, 2021). "Among the top 10 up-regulated DEGs, BMF (BCL2-modifying factor), which interacts with prosurvival Bcl-2 family members to trigger apoptosis, was down-regulated in MCF-7 breast cancer cells as a consequence of induced NeuT overexpression." (PMID 26103053, 2015).
glioma (7 papers, 2012 to 2025). A benign or malignant brain and spinal cord tumor that arises from glial cells (astrocytes, oligodendrocytes, ependymal cells). "Gas5 exerts tumor-suppressive functions in human glioma cells by directly targeting miR-222 and regulating the expression of its targets BMF and Plexin C116." (PMID 29700282, 2018). "The GAS5/miR-222 axis has been suggested to inhibit the BCL-2-modifying factor (BMF) and its downstream BAX protein, thereby delaying the proliferation of glioma cells." (PMID 39941145, 2025).
ovarian carcinoma (7 papers, 2019 to 2025). A malignant neoplasm originating from the surface ovarian epithelium. "Most importantly, FBW7 elevates BMF mRNA level and is positively associated with BMF expression in primary ovarian cancer tissues." (PMID 33658012, 2021). "Carcinogenic YTHDF2 is degraded by FBW7 via interaction, which stabilizes m6A‐modified mRNA, including the pro‐apoptotic gene BMF, and impairs the survival and proliferation of ovarian cancer cells." (PMID 40919129, 2025). "FBW7 interacts with and degrades the oncogenic YTHDF2, consequently leading to stabilization of m6A-modified mRNAs, including the pro-apoptotic gene BMF, and impairment of ovarian cancer cell survival and proliferation." (PMID 33658012, 2021). "Our study has demonstrated that FBW7 suppresses tumor growth and progression via antagonizing YTHDF2-mediated BMF mRNA decay in ovarian cancer." (PMID 33658012, 2021). "MiR-221 also targets on BCL-2 modifying factor (BMF) promoting cell proliferation in ovarian cancer cell line SKOV3." (PMID 31929798, 2019). "Furthermore, FBW7 interacts with and promotes proteolytic degradation of YTHDF2, thereby stabilizing the pro-apoptotic BMF mRNA and evoking apoptosis of ovarian cancer cells." (PMID 33658012, 2021). "Importantly and in line with these in vitro results, we also revealed that the expression of BMF is inversely correlated with YTHDF2 expression, whereas is positively associated with FBW7 expression, in ovarian cancer tissues." (PMID 33658012, 2021). "FBXW7 targets YTHDF2 protein, the m6A reader of BMF mRNA, rescuing the YTHDF2-mediated inactivation of BMF mRNA and repressing the growth and progression of ovarian cancer." (PMID 35814468, 2022). "Collectively, our results clearly demonstrate that FBW7 provokes the expression of pro-apoptotic BMF through an m6A-dependent mechanism by interacting with and degrading the m6A reader YTHDF2 in ovarian cancer." (PMID 33658012, 2021). "Moreover, they found that miR-221 inhibits apoptosis by targeting BMF in HCC and ovarian cancer cells." (PMID 33712023, 2021).
lung carcinoma (6 papers, 2015 to 2024). "Mechanically, an effective ingredient combination of CPPP induces protective autophagy and apoptosis in lung cancer cells through the AMPK–mTOR–ULK1/BMF signaling pathway." (PMID 39598428, 2024). "In EGFR-mutated lung cancer cells, SOX2 overexpression promotes resistance to erlotinib by repressing the expression of proapoptotic proteins BIM and BMF." (PMID 38096163, 2023). "Previously, BMF was verified to be a target of miR-34c-5p and contributed to resistance to apoptosis induced by paclitaxel in lung cancer." (PMID 30654331, 2019). "We found that BQZC could inhibit lung cancer cell growth and induce protective autophagy and apoptosis in lung cancer cells by activating the AMPK–mTOR–ULK1/BMF signaling pathway." (PMID 39598428, 2024). "In summary, this study developed effective ingredient combinations with specific components and clear contents from CPPP that are expected to treat lung cancer and attempted to reveal the interaction between autophagy and apoptosis in tumor cells via the AMPK–mTOR–ULK1/BMF pathway." (PMID 39598428, 2024). "Moreover, several targets of miR-197-3p have been reported in lung cancer cells, including NOXA, Bcl-2-modifying factor (BMF) and lysine 63 deubiquitinase (CYLD)." (PMID 36494333, 2022).
multiple myeloma (6 papers, 2016 to 2026). "Indeed, previous studies in the myeloma cell line U266 have reported that siRNA-mediated knockdown of BMF is associated with a decrease in apoptosis following treatment with arsenic trioxide, whereas mice lacking Bmf develop a B cell lymphadenopathy caused by a resistance of B cells to apoptosis." (PMID 27524613, 2016). "At the same time, arsenic trioxide led to an increase in BMF expression in multiple myeloma." (PMID 40849581, 2026). "Moreover, we found that YY1 mutation could affect the expression changes of certain genes in some cancers; for example, in multiple myeloma, YY1 mutation could affect the expressions of ERMN, DUSP8, PRG2, BMF, and RNASE2 genes." (PMID 35791393, 2022). "Besides, BMF inhibition promotes survival outcomes in multiple myeloma patients." (PMID 33712023, 2021).
chronic lymphocytic leukemia (4 papers, 2016 to 2024). "Some evidence has linked the BMF gene 15q15.1 risk locus to an increased chronic lymphocytic leukemia (CLL) risk." (PMID 37501079, 2023). "For example, rs539846 located in a SE affects chronic lymphocytic leukemia susceptibility through differential binding to RELA (NF-kappa-B subunit) and direct modulation of BMF expression, impacting the antiapoptotic protein B cell lymphoma 2 (BCL2)." (PMID 38410974, 2024).
hepatocellular carcinoma (3 papers, 2015 to 2024). A malignant tumor that arises from hepatocytes. "Over-expression of miR-221 is associated with a more aggressive phenotype of hepatocellular carcinoma and inhibits apoptosis by binding to BMF." (PMID 26690468, 2015). "Previous study shows that TGF-β signaling pathway can regulate cell apoptosis by upregulating BIM, BMF, DAPK expression, and TAT induces hepatoma cell apoptosis by activating caspase-9." (PMID 38769521, 2024).
Hyperglycemia (3 papers, 2019 to 2023). An increased concentration of glucose in the blood. "BMF, a pro-apoptotic gene, has been found to play a key role in regulating different cell functions under hyperglycemia." (PMID 36818559, 2023). "They found out that Bcl2-modifying factor (Bmf), a pro-apoptotic protein is induced by hyperglycemia via ROS and growth factor (TGFβ1) and upregulated in diabetic kidneys of rats and humans." (PMID 33562428, 2021). "Bcl-2 modifying factor (BMF) has been reported to play an important role in the regulation of cell functions under hyperglycemia." (PMID 30654331, 2019). "Bcl-2 modifying factor (BMF), a pro-apoptotic gene, plays a crucial role in regulating different cellular functions under hyperglycemia and promotes apoptosis in renal proximal tubular cells in diabetic mice." (PMID 36818559, 2023).
neuroblastoma (3 papers, 2020 to 2023). Neuroblastoma (NB) is the most common solid, extracranial childhood tumor. "Because BMF has been previously linked to anoikis, we investigated the role of BMF in neuroblastoma." (PMID 38014922, 2023). "We identified the proapoptotic BCL-2 modifying factor (BMF) as a critical player in ATF5-regulated neuroblastoma anoikis." (PMID 38014922, 2023). "Neuroblastoma cells also displayed relatively high expression of BH3-only proteins like BIM, PUMA and NOXA, with strikingly high expression of BMF in the SJNB-12 cells." (PMID 32203216, 2020). "We found that ATF5 knockdown reduced the expression of BCL-2 and MCL-1, but not of BMF, in adherent neuroblastoma cells." (PMID 38014922, 2023).
bladder cancer (2 papers, 2021 to 2023). "In bladder cancer (BC), miR-183-5p regulates cell apoptosis by targeting PNPT1 and BMF to inhibit the outer mitochondrial membrane permeability of BC cells." (PMID 37372440, 2023). "In bladder cancer (BC), miR-183-5p regulates BC cell apoptosis by targeting PNPT1(Polyribonucleotide nucleotidyl transferase 1) and BMF(Bcl2 modifying factor) to inhibit the outer mitochondrial membrane permeability of BC cells." (PMID 37372440, 2023).
lymphoma (2 papers, 2020 to 2021). A malignant (clonal) proliferation of B- lymphocytes or T- lymphocytes which involves the lymph nodes, bone marrow and/or extranodal sites. "Disruption of pro-apoptotic BCL2 family genes [e.g., BAD, BIM, BMF, PUMA] also accelerates lymphoma development in the Eμ-myc model." (PMID 33651821, 2021).
melanoma (2 papers, 2019 to 2023). A malignant, usually aggressive tumor composed of atypical, neoplastic melanocytes. "While vemurafenib induced BMF overexpression, BMF silencing conferred BRAFi resistance and was detected in drug-resistant melanoma cells." (PMID 37834284, 2023).
Stroke (2 papers, 2021). Sudden impairment of blood flow to a part of the brain due to occlusion or rupture of an artery to the brain. "Silencing of BMF reduced infarct volume and apoptosis in the stroke model." (PMID 33546766, 2021). "Similarly, miR-874-3p has been shown to protect stroke patients from ischemic neuronal injury by inhibiting the pro-apoptotic factors BMF and BCL2L13." (PMID 34830203, 2021).
endometriosis (1 paper, 2025). The growth of functional endometrial tissue in anatomic sites outside the uterine body. "The clustering analysis, which reveals pain-related genes (SRP14/BMF, GDAP1, MLLT10, BSN, and NGF), further solidifies the genetic basis for the chronic and often debilitating pain experienced by patients with endometriosis." (PMID 41516028, 2025).
gastric cancer (1 paper, 2022). A primary or metastatic malignant neoplasm involving the stomach. "We showed an increased BMF gene expression after trastuzumab, cetuximab and afatinib treatment in gastric cancer cell lines." (PMID 35264144, 2022). "However, BMF gene expression was not confirmed as biomarker for overall survival in trastuzumab-treated or non-trastuzumab-treated gastric cancer patients." (PMID 35264144, 2022).
ischemic stroke (1 paper, 2017). A stroke disorder caused by obstruction of blood flow to the brain, due to thrombotic (local blood clot formation) or embolic (due to a blood clot or other material traveling from another site) event. "Results from prior studies show that IL21R, BMF, and GPNMB correspond to mediators of injury following ischemic stroke." (PMID 28097054, 2017).
leukemia (1 paper, 2016). A malignant (clonal) hematologic disorder, involving hematopoietic stem cells and characterized by the presence of primitive or atypical myeloid or lymphoid cells in the bone marrow and the blood. "Loss of BCL2 modifying factor (BMF), a proapoptotic member of the BCL2 family, was recently shown in a single nucleotide polymorphism (SNP) array study to play a role in the development and relapse of ETV6/RUNX1 positive leukemia." (PMID 26919255, 2016).
liver cancer (1 paper, 2024). An epithelial or non-epithelial malignant neoplasm that arises from the liver. "In addition, miR-221-5p has been reported to be involved in the progression of various tumors; for example, miR-221 was found to inhibit the apoptosis of liver cancer cells by targeting BMF, and overexpression of miR-221 promoted cell invasion." (PMID 39439418, 2024).
mesothelioma (1 paper, 2022). A usually malignant and aggressive neoplasm of the mesothelium which is often associated with exposure to asbestos. "Taken together, we demonstrate that TEAD inhibition could be an exploitable vulnerability across multiple malignant tumor models besides mesothelioma and that upregulation of BMF gene is a common phenomenon in those cancer cells with sensitive antiproliferative response to TEAD inhibitor." (PMID 36300789, 2022).
non-small cell lung carcinoma (1 paper, 2023). A group of at least three distinct histological types of lung cancer, including non-small cell squamous cell carcinoma, adenocarcinoma, and large cell carcinoma. "YAP/TEAD/SLUG association has been shown to mediate the resistance to combined EGFR/MEK inhibition by inducing dormancy in non-small-cell lung cancer cells, through the direct inhibition of the pro-apoptotic protein BMF (Bcl2 Modifying Factor)." (PMID 38124183, 2023).
pancreatic cancer (1 paper, 2023). "Three genes (ABCA12, B3GNT3, and BMF) and eight miRNA (hsa.miR.577, hsa.miR.503, hsa.miR.3613, hsa.miR.19a, hsa.miR.19b.2, hsa.miR.365a, hsa.miR.365b, and hsa.miR.4668) were found to be dysregulated in four different stages of pancreatic cancer." (PMID 37794108, 2023).
uveal melanoma (1 paper, 2023). A melanoma derived from melanocytes of the uveal tract. "A recent in vitro study indicated that HGF promotes resistance to MEK inhibitors by increasing the expression of the proteins, Bcl-2-like 11 (BIM)—extra-long (EL) and Bcl-2 Modifying Factor (BMF), in uveal melanoma cells." (PMID 37576814, 2023).
viral infection (1 paper, 2023). "As per viral infection, NIC and virus treated cells (at 48 h) also saw an up-regulation of GABARAPL1, MAP1LC3A, USP30, BMF, and TBK1; WDR81 was also down-regulated in the NIC and virus treatment at 48 h." (PMID 37901834, 2023).